VIM (vimentin)
Diseases named in the same sentence as VIM in open-access papers (continued):
Sharing a sentence is not in itself a finding about the gene and the disease.
meningioma (continued). "Following subcutaneous and orthotopic transplantation of low passage cells into SCID mice, firm tumors positive for vimentin and progesterone receptor (PR) formed, while subcutaneous implant of high passage cells yielded vimentin-positive, PR-negative tumors, concordant with a high-grade meningioma." (PMID 26174772, 2015). "Moreover, we purified one phosphorylated form of vimentin acting as an accurate marker for specific and sensitive identification of noninvasive meningiomas." (PMID 20169076, 2010). "Vimentin intermediate filament expression has been characterized extensively using immunohistochemistry in the cells of the arachnoid membrane, granulations, and meningiomas, as well as in cultured human leptomeningeal cells." (PMID 16223448, 2005). "Meningioma cells are derived from benign tumours (meningiomas) of the human leptomeninges and they share the same morphology, cytological structure and expression of cell markers (desmosomal desmoplakin, cytokeratin, vimentin and epithelial membrane antigen) as normal leptomeningeal cells." (PMID 24833056, 2013). "Immunohistochemical profiling demonstrated diffuse immunoreactivity for vimentin, progesterone receptor (PR), and epithelial membrane antigen (EMA), with focal SSTR2A positivity - a staining pattern pathognomonic for meningioma." (PMID 40727478, 2025). "The diagnosis of meningioma can be confirmed by immunohistochemical stains since most meningiomas express EMA (epithelial membrane antigen,), progesterone receptor, and vimentin." (PMID 36230612, 2022). "To confirm the effect of curcumin on EMT in meningioma, we used western blot to determine the expression of EMT marker proteins (E-cadherin, N-cadherin, and vimentin)." (PMID 34408780, 2021). "This enabled validation of peptides of several candidate biomarkers like VIM, ANXA2, AHNAK, TS101, and CLIC1 from the surgically resected meningioma tissues and control arachnoid regions." (PMID 32974197, 2020). "In meningiomas, E-cadherin expression is negatively correlated with WHO grade and invasion, while vimentin is increased with higher malignancy grades." (PMID 28340489, 2017). "The tumor cells in our report showed positive staining for vimentin and EMA, which further support the diagnosis of meningioma." (PMID 25896915, 2015). "Western blot analysis showed that meningioma cells of all subtypes expressed EMA, vimentin, and VEGF proteins." (PMID 22754374, 2012). "In contrast, high-grade or sarcomatous meningiomas may lose expression of EMA, PR, and vimentin, necessitating molecular confirmation of meningothelial origin." (PMID 41552249, 2025). "The use of vimentin, which strongly stained this meningiomas, alongside cytokeratin, which did not stain this meningioma, allowed clear differentiation between the two neoplastic populations in the body." (PMID 41560863, 2025). "Using immunocytochemical analysis, protein expressions of vimentin (Vim) and somatostatin receptor 2A (SSTR2A) were observed in these two primary benign meningioma cells (WHO grade I) including the well-established meningioma cell lines—HKBMM and IOMM-Lee (WHO grade III)." (PMID 38274327, 2024). "Vimentin and EMA are the two important markers to confirm extra-cranial meningioma diagnosis." (PMID 32850120, 2020). "According to the available immunohistochemical results of published cases, the meningioma components were often positive for EMA, PR, and vimentin (except for 1 case of secretory meningioma), and the pulmonary carcinoma components were frequently positive for TTF-1 and CK7." (PMID 33126391, 2020). "Sub regions that showed multiple co-staining of markers including CD133, Frizzled 9, GFAP, Vimentin, and SSEA4, but not necessarily the proliferation marker Ki67, were highly associated with grade II/III meningiomas." (PMID 29849507, 2018).
meningioma (continued). "Identified proteins like vimentin, alpha-2-macroglobulin, apolipoprotein B and A-I and antithrombin-III, which exhibited a sequential increase in different malignancy grades of meningiomas, could serve as potential predictive markers." (PMID 25413266, 2014). "Meningioma cells of all subtypes of tumors were positive for human epithelial membrane antigen (EMA) and vimentin staining and desmoplakin staining, and negative for markers of neural cell types such as GFAP for astrocytes and β-tubulin III for neurons (data not showed)." (PMID 22754374, 2012). "Immunostaining for vimentin and EMA reinforced the meningothelial nature of this atypical lesion, not only in the present case but in other unusual intracerebral tumors with regions reminiscent of meningioma." (PMID 22011733, 2011). "The tumor cells showed intense reactivity for EMA and vimentin, but not for CK and S-100 protein, findings that are consistent with the diagnosis of meningioma." (PMID 21722387, 2011). "Commercially available polyclonal antibodies directed against seven different phosphorylated-vimentin peptides were used in Western blots to identify specific vimentin phosphosites in lysates from noninfiltrative or infiltrative meningiomas." (PMID 20169076, 2010). "Additional investigations are therefore required to identify the specific phosphorylated amino acid residues in the vimentin form that is present in greater amount in noninfiltrative meningiomas." (PMID 20169076, 2010). "Antibodies against EMA, vimentin and Ki-67 have been used to provide histopathological differential diagnoses of meningioma and to estimate its malignancy grade; however, no molecular marker that is specific for meningiomas has been described to date." (PMID 20199689, 2010). "Finally, this study demonstrated that in meningiomas, an increase of vimentin concentration is probably not a molecular event indicative of invasiveness per se but more accurately the presence of the protein in a multiphosphorylated form is an indicator for noninvasiveness." (PMID 20169076, 2010). "Immunohistochemically, HPCs typically express markers such as CD34, vimentin, CD99, and Bcl-2 while being negative for S100, which helps differentiate them from other spindle cell neoplasms like schwannomas or meningiomas." (PMID 39371697, 2024). "Regions that were significantly frequently occurring in grade II/III but never in grade I meningiomas included those that were positive for CD133+SOX2±Vimentin+FZD9+GFAP+BTIII+SSEA4+Olig2+, and Nestin+Ki67+CD133+Vimentin+FZD9+GFAP+BTIII+SSEA4+Olig2+." (PMID 29849507, 2018). "The majority of meningiomas stains positively for EMA, vimentin and somatostatin receptor 2A, but none of these are specific for this tumor." (PMID 28953948, 2017). "However, EMA and vimentin are not useful to differentiate between meningioma and perineuroma as they both express positivity for EMA and vimentin but perineuroma the cells are spindle and elongated however, in our case they are rounded and polyhederal (meningiothelial pattern)." (PMID 32850120, 2020).
liver cancer (51 papers, 2012 to 2025). An epithelial or non-epithelial malignant neoplasm that arises from the liver. "The relationship between Bcl-2/Twist1 and Bcl-2-Bmi1 promotes EMT and development of VM through loss expression of E-cadherin and increased vimentin expression in hepatic cancer cells." (PMID 31993365, 2019). "Therefore, to investigate the correlation between each NFYA variant and PCK1 in 297 liver cancers using RNA-seq data from TCGA, we classified by the logFC of VIM/CDH1 into two groups: those predominantly expressing NFYAv1 (1 < logFC) and those predominantly expressing NFYAv2 (logFC < −1)." (PMID 36092708, 2022). "Exosomes from highly invasive liver cancer cell lines downregulate E-cadherin expression and upregulate vimentin expression in recipient cells." (PMID 40486884, 2025). "The co-culturing of macrophages treated with exosomes from both groups with liver cancer cells showed that the levels of ZEB-1 and vimentin in liver cancer cells were downregulated, while the level of E-cadherin was upregulated." (PMID 40612677, 2025). "The expression of E-cadherin was increased, while the expression of vimentin was decreased, indicating that this drug inhibited liver cancer metastasis." (PMID 38560575, 2024). "UCHL3 promoted migration of the liver cancer cells of the current study by deubiquitinating Vimentin." (PMID 36969045, 2023). "The LINC01010 interferes with vimentin polymerization and then inhibits the proliferation and migration ability of liver cancer cells." (PMID 36052283, 2022). "The results of the present study are in concordance with published results for liver cancer cells: these cells become spindle-shaped, lose E-cadherin expression, and gain mesenchymal markers such as vimentin when resistance to sorafenib develops." (PMID 36138026, 2022). "Increased expression of vimentin has been observed in colorectal, breast, gastric, and hepatic cancers." (PMID 33757532, 2021). "In hepatic cancer HepG2 and MHCC97-H cell lines, the Notch1 expression was higher in HepG2 favoring invasiveness by inducing the EMT through an increase in vimentin and loss of E-cadherin expression." (PMID 31993365, 2019). "In parallel with our previous observation, miR-31 selectively regulated EMT proteins, N-cadherin, E-cadherin, vimentin and fibronectin, to control metastatic potential of liver cancer cells." (PMID 25797269, 2015). "E-cadherin knockout mice will develop spontaneous liver cancer and the loss will promote chemical induced (with diethylnitrosamine) liver cancer with strong expression of stem cell marker CD44 and EMT marker vimentin." (PMID 25197668, 2014). "Another highlight should be addressed is that the PP treatment resulted in a reduced invasiveness of liver cancer cells, which was further supported by the decreased protein expressions of N-cadherin and vimentin in PP-treated cells." (PMID 22470568, 2012). "Similarly, the expression of Vimentin was highly increased by exogenous Axl expression in the human liver cancer cell lines Hep3B and Huh7, while the expression of E-Cadherin was downregulated, emphasizing the role of Axl in the EMT." (PMID 38673795, 2024).
liver cancer (continued). "In in vitro models of liver cancer cell lines, the downregulation of miR-129-3p was associated with a reduced expression of epithelial markers (Cadherin 1 [CDH1] and CTNNB1) and an increase in mesenchymal markers (Cadherin 2 [CDH2] and Vimentin [VIM]))." (PMID 39598228, 2024). "In the radioresistance liver cancer cell models, HepG2R and Hep3B, the combination treatment of fisetin and radiation overcame radioresistance and induced apoptotic cell death by downregulating N-cadherin and vimentin and upregulating E-cadherin." (PMID 37240422, 2023). "The results demonstrated that, compared with the blank control vector (Vector), the overexpression model might dramatically promote E-cadherin expression in liver cancer cells whilst decreasing N-cadherin and Vimentin expression in SMMC-7721 cells." (PMID 35260047, 2022). "Compared with the blank control vector (sh-Control), the knockdown model could significantly suppress E-cadherin expression in liver cancer HB611 cells whilst promoting N-cadherin Vimentin expression." (PMID 35260047, 2022). "Vimentin can affect the apoptosis of SMMC-7721 cells in liver cancer studies." (PMID 35126515, 2022). "In the current study, silencing of FASN, FSCN1 or SPTBN1 expression in liver cancer cells led to changes in the mRNA expression of EMT-associated markers, E-cadherin, N-cadherin, vimentin and transcription factors Snail and Twist, and altered the protein expression of MMP-2 and MMP-9." (PMID 32699531, 2020). "Western blotting and immunostaining demonstrated a remarkable increase in the expression of β2-AR, YB-1, N-cadherin and vimentin and decrease in the expression of E-cadherin, which are governed by the β2-AR/YB-1 axis, in liver cancer tissues from mice subjected to chronic stress." (PMID 32973139, 2020). "Furthermore, hematoxylin and eosin (H&E) and immunofluorescence staining showed that original HCC tissues expressed alpha‐fetoprotein (AFP, liver cancer marker) and vimentin (VIM, stromal cell marker) and exhibited high expression of Ki67 (cell proliferation marker)." (PMID 37485650, 2023). "Voluntary swimming decreased the protein expression of transforming growth factor-β1 (TGF-β1), vimentin, and N-cadherin and increased the expression of E-cadherin, while forced prolonged swimming had the opposite effect on the expressions of those molecules in liver cancer tissue." (PMID 31936342, 2020). "Thus, the associations between vimentin and clinicopathological characteristics in NSCLC may be inconsistent to other cancers, like MBC, liver cancer." (PMID 27657690, 2016). "Vimentin, EMT reprogramming protein, confers migratory and invasive phenotypes and is highly expressed in hepatic cancers." (PMID 37142825, 2024). "The immunofluorescence staining showed that highly positive staining signals with liver cancer cells (AFP), and proliferate cell (Ki67) and MC (vimentin)." (PMID 34439154, 2021). "Immunofluorescence staining showed highly positive staining signals with liver cancer cells (AFP), iPSC-EC (hCD31), and iPSC-MC (vimentin) in vitro." (PMID 34439154, 2021). "In contrast, knockdown of LINC01234 greatly decreased the expression of vimentin and α-SMA in liver cancer cells." (PMID 33178601, 2020). "But literature reviews suggest that overexpression of EMT-TFs factors (e.g.vimentin) have a significate correlated to another cancer, like MBC, liver cancer." (PMID 27657690, 2016).
liver cancer (continued). "Also, a study of human liver cancer cell lines showed that CT83 affects EMT markers, such as E-cadherin, N-cadherin, vimentin, and Snail at protein levels." (PMID 40141328, 2025). "In the human liver cancer cell lines Hep3B and LM3, knockdown of CREB5 increased the expression of the epithelial marker E-cadherin but decreased that of the mesenchymal markers N-cadherin and vimentin, as well as the EMT transcription factor Snail." (PMID 39915455, 2025). "In western blot analysis, overexpression of Fascin-1 reduced the expression of E-cadherin and increased the expression of N-cadherin and Vimentin in HepG2 cells, indicating that forced Fascin-1 expression promoted EMT of liver cancer cells under both normoxia and hypoxia conditions." (PMID 34897283, 2021). "Moreover, in the process of liver cancer metastasis, HIF-1α regulates zinc finger transcription factors to affect the expression of EMT markers, such as E-cadherin, N-cadherin, and vimentin, and promotes invasion and metastasis." (PMID 34335854, 2021). "This hypothesis was supported by the finding that expression levels of SNAIL1 were significantly correlated with VIM (Vimentin) and TWIST1 in 423 liver cancer patients (TCGA liver cancer)." (PMID 30405889, 2018). "However, regardless of whether treated with sorafenib or not, overexpression of TRIB3 did not affect the migration of liver cancer cells, nor did it alter the expression of E‐cadherin and vimentin." (PMID 39932456, 2025). "To examine whether HOTAIR regulates EMT in liver cancer cells through NUAK1, we transfected cells with the HOTAIR overexpression plasmid (P-HOTAIR) followed by addition of the NUAK1 inhibitor HTH-01-015 and then detected EMT markers E-cadherin, N-cadherin, and Vimentin by western blot." (PMID 37576402, 2023).